AHR (aryl hydrocarbon receptor)
Diseases named in the same sentence as AHR in open-access papers (continued):
Sharing a sentence is not in itself a finding about the gene and the disease.
tumor (continued). "Exposure to DLCs produces a wide variety of biologic and toxic effects such as teratogenesis, immunosuppression, and tumor promotion, most of them dependent on the activation of the aryl hydrocarbon receptor (AhR)." (PMID 16203240, 2005). "Therefore, the study proposes a novel therapeutic strategy: IFN-γ combined with IDO1 or AhR inhibitor can disrupt the dormancy of TRCs and induce their apoptosis, thus achieving more effective tumor clearance." (PMID 41438587, 2026). "Since a growing body of evidence indicates that AHR activation is involved in the proliferation, survival, migration, and invasion of tumor cells, the inhibition of AHR activation through AHR antagonists has emerged as a broadly efficient therapeutic strategy in experimental oncology." (PMID 41540003, 2026). "The Kyn-AhR axis has been one of the links between chronic inflammation and tumor progression, which may also become a potential target for AMI therapy." (PMID 40147625, 2026). "Our findings indicate that targeting PRMT3 in tumor cells and inhibiting Kyn metabolism not only suppresses tumor growth but also significantly mitigates the development of an immunosuppressive microenvironment by activating AhR." (PMID 41129671, 2026). "CONCLUSIONS: These findings reveal a previously unrecognized regulatory axis controlling HLA-II expression on cancer cells, suggesting that targeting the AHR-ARNT pathway may enhance tumor immunogenicity and improve immunotherapy efficacy." (PMID 41721339, 2026). "Notably, ZSTK3744 demonstrated superior tumor inhibition and lower pulmonary toxicity in ex vivo and in vivo models than other AhR agonists." (PMID 41628058, 2026). "Lactobacillus reuteri has been shown to metabolize dietary tryptophan into AhR agonists, such as indole-3-aldehyde, which activate AhR signaling in tumor-infiltrating CD8+ T cells, thereby enhancing IFN-γ production, antitumor immunity, and responsiveness to immune checkpoint blockade." (PMID 41602751, 2026). "Whether promoting tumor suppression or progression, AHR acts as a central hub that integrates environmental, dietary, microbial, and metabolic inputs into coordinated responses." (PMID 41540003, 2026). "However, persistent AHR activation can adversely affect immune defense mechanisms, induce cell dedifferentiation, promote tumor immune evasion, and contribute to therapeutic resistance." (PMID 41513604, 2026). "Distinct miRNA signatures emerged: high-dose B[a]P enriched miRNAs linked to cancer progression, whereas lung microbiota alone or with low-dose B[a]P induced tumor-suppressor miRNAs that limit proliferation and metastasis and promote apoptosis, an effect enhanced by AHR antagonism." (PMID 42041582, 2026). "Combining AHR modulators with checkpoint inhibitors may help promote a more effective tumor-killing Th1 profile." (PMID 41357201, 2025). "In some studies, AhR has also shown the ability to inhibit tumor growth." (PMID 40103267, 2025). "In our recent studies on environmental As3+-induced malignant transformation, biochemical analyses and ChIP-seq data suggested that AHR may exert tumor-suppressive effects by antagonizing TGF-β and Nrf2 signaling pathways." (PMID 40303305, 2025). "Collectively, these findings suggest that the role of AhR in anti-tumor immunity could be cancer type-specific." (PMID 41331250, 2025). "AhR can influence the makeup of the gut microbiota by regulating other cytokines and signaling pathways, which can further affect the immune status of the intestinal tract and tumor progression." (PMID 41019044, 2025). "Additionally, tumour recurrence following ADT was delayed by pharmacological suppression of TDO2-Kyn-AhR signalling with a TDO2 inhibitor or an AhR inhibitor." (PMID 40759641, 2025).
tumor (continued). "Subsequently, it was observed that AhR is involved in various physiological processes such as immune system regulation, hepatic homeostasis, cardiac development, wound healing, cell proliferation and apoptosis, metabolic diseases, and tumor promotion." (PMID 40141386, 2025). "In cases of chronic inflammation, the activation of the AhR/IL-22 pathway might result in the unusual growth of intestinal epithelial cells and the development of tumor." (PMID 41019044, 2025). "Importantly, IDO2 expression closely mirrored that of AhR and tumour cell density, reinforcing a potential regulatory link between the two." (PMID 40471422, 2025). "Nonetheless, IDO2 expression was closely aligned with AhR expression and tumour cellularity, while no such association was found between AhR and either IDO1 or TDO2." (PMID 40471422, 2025). "Triggers AhR signaling to drive tumor invasion and enhance cancer stemness." (PMID 41181090, 2025). "However, as the tumor progresses, the function of AhR undergoes a significant shift from tumor suppression to promoting malignancy." (PMID 41585883, 2025). "Moreover, both cellular and animal experiments have demonstrated that heightened TDO2 expression in tumor cells results in the release of Kyn, which activates AhR." (PMID 40136551, 2025). "Moreover, the metabolic byproducts of tryptophan bind to the aryl hydrocarbon receptor, counteracting signals that activate T cells and facilitating the immune evasion of tumor cells." (PMID 40217479, 2025). "In certain tumor types, a microbiota–Trp–AhR axis potentiates antitumor immunity." (PMID 41516132, 2025). "For instance, an earlier study illustrated that hyperactivity of AhR may allow tumor survival and escape immune surveillance by activating pro-inflammatory signaling and establishing an immune-suppressive tumor microenvironment." (PMID 39791758, 2025). "Moreover, in adenomatous polyposis coli (APC), a key tumor suppressor gene, deficient CRC, tryptophan 2,3-dioxygenase 2 (TDO2) was identified as an essential effector that, via Kyn-AhR pathway, upregulate glycolysis and anabolic cancer cell growth." (PMID 40361394, 2025). "In the preoperative setting, doubling the aryl hydrocarbon receptor (AhR) was achieved, which may influence tumor activation." (PMID 40944112, 2025). "HIF-1α and ER would be highly active in AHR-high ER+ tumours." (PMID 40646277, 2025). "This paradox—the shift from tumor suppression to oncogenesis—highlights a critical gap in current research and points toward future investigative directions: A deeper exploration of the molecular mechanisms governing this functional switch in AhR is crucial." (PMID 41585883, 2025). "To further ensure that the observed immunological differences were not driven by clinical or demographic imbalances, we compared the tumor stage (T, N, M), histological grade (G), age, sex, and serum CA 19–9 levels between the Low and High/Medium AHR expression groups." (PMID 41357201, 2025). "For example, it has been shown that IAld and IAA promote the differentiation of monocytes into dendritic cells and enhance the phagocytic activity of neutrophils and macrophages, and that tryptophan activates the AHR pathway in NK cells, which enhances cytotoxicity against tumor cells." (PMID 40066456, 2025). "Further, among the I3P‐derived metabolites, kynurenic acid (KynA) and indole‐3‐aldehyde (I3A) lead to the activation of the AHR signalling pathway, which might increase the migratory and invasive abilities of tumour cells and reduce CD8+ T cell proliferation." (PMID 40071723, 2025). "To this end, we first evaluated the tumor‐suppressive role of AhR in vivo." (PMID 40557796, 2025). "However, I3A treatment of AhR‐knockdown B16‐OVA cells resulted in further enhancement of T cell activation, suggesting the involvement of additional factors beyond AhR for I3A‐induced tumor immunogenicity." (PMID 40583248, 2025).
tumor (continued). "However, in pancreatic tumors, gut microbiota‐derived indole activates macrophages in the pancreas, and AhR activation suppresses antitumor immunity, leading to tumor‐promoting features." (PMID 40103267, 2025). "Consequently, sustained activation of this IDO1/Kyn/AhR pathway potently facilitates tumour immune escape." (PMID 41275427, 2025). "Additionally, KYN activates the aryl hydrocarbon receptor (AhR), which drives immune suppression and facilitates tumor growth and metastasis." (PMID 39997327, 2025). "High-frequency terms such as “gut microbiota,” “tumor microenvironment,” “aryl hydrocarbon receptor,” and “cancer immunotherapy” suggest a paradigmatic shift from single-pathway metabolic studies toward integrated perspectives that encompass metabolic–immune–microbial interactions." (PMID 40666095, 2025). "The inconsistent behavior between TRCs and regular tumors may be due to the differential expression patterns of IDO1 and AhR in tumor stem cells." (PMID 40103267, 2025). "This hypothesis is supported by studies in models where AHR was deleted or suppressed, resulting in increased Wnt activity and enhanced tumor development." (PMID 40765830, 2025). "Indoleamine 2, 3-dioxygenase 1 (IDO1) is a rate-limiting enzyme that converts the essential amino acid tryptophan into downstream kynurenine (Kyn), indicated as a novel mechanism for blocking the proliferation and anti-tumor activity of immune cells by activating the aryl hydrocarbon receptor (AhR)." (PMID 39863603, 2025). "Notably, other AHR ligands present in the tumor microenvironment, such as indole-derived metabolites, can bind to AHR and influence immune responses." (PMID 40283908, 2025). "IDO1 activity suppresses T-cell activity by depleting tryptophan, which is required for Th1 and CD8+ T-cell-mediated immunity, while kynurenine binds to the aryl hydrocarbon receptor (AHR), which directly activates Treg differentiation and activity, resulting in reduced anti-tumor responses." (PMID 41235226, 2025). "Activation of AHR signaling with tryptophan metabolites such as kynurenine (Kyn), an endogenous AHR ligand which is upregulated during inflammation and/or tumor progression, was shown to suppress the IFN-I response after infection with either RNA or DNA viruses." (PMID 40128585, 2025). "To identify the different sets of genes activated by AhR at different phases of tumour progression, we carried out CUT&Tag chromatin profiling to investigate the differential AhR signalling in three different cell conditions: LNCaP cells, LNCaP cells with 7 days of ADT and LNCaP-EnzR cells." (PMID 40759641, 2025). "Additionally, these metabolites promote tumor malignancy and attenuate antitumor immune responses through aryl hydrocarbon receptor (AHR) activation." (PMID 40948940, 2025). "The role of AHR in cancer in general is still debated and it may differentially affect tumour cells and immune cells." (PMID 40212817, 2025). "Interactions between STING and AhR have been previously reported in macrophages and tumor cells." (PMID 41321306, 2025). "The results suggest a central and complex role for the AhR in controlling tumor immunity." (PMID 40449595, 2025). "All three metabolites activate AhR, enhancing tumor cell motility and invasiveness." (PMID 40103267, 2025). "In contrast, DNA repair pathways were enriched in AHR-low tumours." (PMID 40646277, 2025). "The gut microbiome secreted many metabolites in the tumor microenvironment, such as short-chain fatty acids (SCFAs), formate, and tryptophan-derived indoles, which promoted immune tolerance and metastasis via AHR signaling." (PMID 40765830, 2025). "During the initiation stage of HCC, AhR primarily acts as a tumor suppressor." (PMID 41585883, 2025). "AHR is overexpressed in various tumors, including pancreatic cancer, suggesting that it could serve as an important drug target for certain tumor types." (PMID 40771930, 2025).
tumor (continued). "These typtophan metabolites could maintain immune homeostasis of the intestine, skin and tumor microenvironment in an AhR-dependent manner." (PMID 39979552, 2025). "In addition to the AhR pathway, the depletion of Trp in the tumor microenvironment can also exert an immunomodulatory effect." (PMID 41332472, 2025). "Regardless of the situation, it is certain that KYNA can promote tumor immune evasion via AhR." (PMID 40103267, 2025). "Kynurenine produced by tumor cells activates the aryl hydrocarbon receptor (AHR) in GAMs." (PMID 40642066, 2025). "Moreover, mounting evidence over the past few years has suggested a tumor-suppressive nature of AHR in both cellular and animal tumor models." (PMID 40303305, 2025). "In GH-PitNETs, the elevated IAA may act in a similar way, potentially activating AHR and creating an environment that supports tumor growth by weakening immune defenses." (PMID 40624207, 2025). "Future work will address whether similar AHR mechanisms occur within the tumor microenvironment and TAMs." (PMID 41357201, 2025). "Furthermore, upon AHR depletion, the anti-tumor immunity of polyfunctional CD8+ T cells is diminished, which further strengthens the importance of AHR." (PMID 40989699, 2025). "Upregulating KYNU and degrading kynurenine to weaken kyn‐AhR signaling may be a reliable way to control tumor immunosuppression." (PMID 40103267, 2025). "However, kynurenine–AhR signaling has also been shown to promote an immunosuppressive tumor microenvironment." (PMID 40771692, 2025). "In contrast, some studies highlight the tumor‐suppressive potential of AhR pathway activation." (PMID 41332472, 2025). "The AhR inhibitor CH223191 also strongly suppressed LNCaP-EnzR xenograft tumour growth." (PMID 40759641, 2025). "Furthermore, CH223191 also significantly reduced the expression of CYP1B1, another target gene of AhR, suggesting that AhR inhibition was more effective, which was consistent with the results of tumour growth suppression." (PMID 40759641, 2025). "Given the multiple roles of JAK/STAT signaling in the immune system, the results also suggest multiple levels at which the AhR may affect tumor immunity." (PMID 40449595, 2025). "Additionally, Carbidopa treatment has been shown to increase AHR protein levels while decreasing AR protein levels in tumor tissue." (PMID 40771930, 2025). "These metabolic alterations, including enhanced lipogenesis and glucose uptake, are crucial for tumor cell proliferation and survival, suggesting that AHR activation may facilitate tumor growth by promoting metabolic flexibility." (PMID 40248203, 2025). "Moreover, PTSK@CRM significantly reduces the contents of Kyn and cholesterol and decreases the activation of the Kyn-AhR pathway in tumor metabolism." (PMID 41432057, 2025). "TDO2 promotes tumor progression in bladder cancer via AhR‐mediated SPARC/FILIP1L signaling." (PMID 41332472, 2025). "The mechanism involves the accumulation of DNA damage, upregulation of proliferation markers, and failure of cell cycle checkpoints, confirming that AhR, under physiological conditions, functions as a tumor suppressor by restraining abnormal cell cycle progression." (PMID 41585883, 2025). "Tumor suppressor gene products can suppress AHR promoter activity." (PMID 40765830, 2025). "Overexpression of IDO1 leads to increased production of KP metabolites in the local cancer microenvironment, and consequently activation of AHR, which results in initiation of tumorigenesis by suppressing antitumor immune responses and promoting tumor cell survival and motility." (PMID 40332338, 2025).
tumor (continued). "Conversely, AhR can inhibit AR signaling through the recruitment of corepressors or the ubiquitin-proteasome pathway, accelerating AR degradation and reducing its transcriptional activity, potentially inhibiting tumor growth." (PMID 39184676, 2024). "Still, in relation to Th17 cells in CRC in an animal model, when the tumor was induced by azoxymethane with dextran sulfate sodium, TGF-β present in the TME induced the differentiation of IL-22-producing Th17 through the expression of aryl hydrocarbon receptor (AHR) contributing to tumor growth." (PMID 38690280, 2024). "Inhibition of AhR can reduce tumor growth in PDAC and improve the response to ICB therapy." (PMID 39031507, 2024). "The controversy surrounding the effect of AhR on carcinogenesis and tumor immunity may be attributed to the type, stage, and degree of cancer malignancy." (PMID 38680496, 2024). "Interestingly, AhR also holds a functional role in the molecular mechanisms governing the development of CSCs, which are well-known tumor-initiating cells, along with being targets for several chemical carcinogens." (PMID 38448800, 2024). "Studies have shown that AhR can enhance AR activity, thereby promoting tumor growth." (PMID 39184676, 2024). "Taken together, these findings strongly suggest a tumor-suppressor-like role of AhR in the colon." (PMID 39767818, 2024). "In our study, we first analyzed the heterogeneity of TAMs in OS tissues based on single-cell data and identified three types of TAMs, CD68 + TAMs, AHR + TAMs, and M0 TAMs, which confirmed that the distribution of M1/M2 macrophage polarization was ambiguous in the actual tumor environment." (PMID 38280909, 2024). "Additionally, given the complex cell-specific role of AhR signaling on immune function within the tumor microenvironment (TME), therapeutic targeting of AhR in cancer requires careful consideration." (PMID 38339226, 2024). "For example, AhR activation in dendritic cells can promote the differentiation of regulatory T cells (Tregs), which are known to suppress anti-tumor immune responses and promote tumor growth." (PMID 39184676, 2024). "It is difficult to rationalise the underlying rationale for these divergent viewpoints on AHR action in a tumour setting, but it will be important to carefully characterise the functional effect of AHR activation or inhibition in different cell types present in the tumour environment." (PMID 39242971, 2024). "The tumor-suppressive effect of B. breve lw01 by activating AhR could be ascribed to its protective catabolites." (PMID 38773969, 2024). "Additionally, AhR controls genes that regulate the cell cycle and apoptosis, influencing tumor growth independently of AR." (PMID 39184676, 2024). "Moreover, AhR-expressing T cells and macrophages were not only observed in the stromal regions, but also within the tumor nest, indicating that AhR is expressed in the immune cells that infiltrated the tumor nest." (PMID 38680496, 2024). "AHR’s autonomous role in tumorigenesis and cancer progression, combined with its immune suppression properties suggest that inhibition of AHR offers an antitumor therapeutic option to reduce tumor growth and help release the “brake” that cancer uses to evade the immune system." (PMID 39450255, 2024). "The co-administration of aminoflavone and histone deacetylase inhibitors can exert an anti-tumor effect on MSL subtypes due to the ability of histone deacetylase inhibitors to sensitize MSL to aminoflavone through improving the reactivity of the aryl hydrocarbon receptor (AhR)." (PMID 38892472, 2024). "Therefore, cancer trends showed a high expression of IDO1 and/or TDO2 to catabolize TRY, generating abundant KYN that further activates AHR and its targets for the sake of tumor progression." (PMID 38347841, 2024). "Interestingly, the expression of AHR and its downstream genes declined at day 18 post-4T1 tumor inoculation." (PMID 39690159, 2024).